MBD3 (methyl-CpG binding domain protein 3)
Description:
Acts as a component of the histone deacetylase NuRD complex which participates in the remodeling of chromatin. Acts as transcriptional repressor and plays a role in gene silencing. Does not bind to methylated DNA by itself. Binds to a lesser degree DNA containing unmethylated CpG dinucleotides. Recruits histone deacetylases and DNA methyltransferases.
Tractability: PROTAC: UniProt records ubiquitination sites on it; ubiquitination databases record sites on it; its protein half-life has been measured.
Gene: Protein-coding gene on chromosome 19 (1,573,596 to 1,592,869, reverse strand). Ensembl gene ENSG00000071655.
Subcellular location: Nucleus; Chromosome
Subcellular location (Human Protein Atlas): Nucleoplasm
Pathways (Reactome):
Gene expression (Transcription): ERCC6 (CSB) and EHMT2 (G9a) positively regulate rRNA expression; RNA Polymerase I Transcription Initiation; Regulation of endogenous retroelements by KRAB-ZFP proteins; Regulation of endogenous retroelements by Piwi-interacting RNAs (piRNAs)
Chromatin organization: HDACs deacetylate histones; Interaction of NuRD complexes with transcription factors; NuRD complex assembly
Developmental Biology: Differentiation of naive CD4+ T cells to T helper 2 cells (Th2 cells); Transcriptional regulation of brown and beige adipocyte differentiation by EBF2
Disease: Potential therapeutics for SARS
Signal Transduction: Regulation of PTEN gene transcription
Gene Ontology:
Molecular function: methyl-CpG binding; nucleosomal DNA binding; protein binding; DNA binding
Biological process: chromatin remodeling; DNA methylation-dependent constitutive heterochromatin formation; negative regulation of DNA-templated transcription; negative regulation of transcription by RNA polymerase II; positive regulation of DNA-templated transcription; regulation of cell fate specification; regulation of stem cell differentiation; embryonic organ development; epigenetic regulation of gene expression; response to bisphenol A; response to estradiol; response to nutrient levels; ventricular cardiac muscle tissue development
Cellular component: chromatin; chromosome; nucleoplasm; nucleus; NuRD complex; protein-containing complex; cytoplasm; heterochromatin
Genetic constraint (gnomAD): Loss-of-function variants: 10 observed, 24.91 expected, observed/expected ratio (o/e) 0.4, 90% interval 0.25 to 0.68. The upper end of that interval is the gene's LOEUF score, 0.68, which puts it in group 2 of 6, group 1 being the genes least tolerant of losing a copy. Missense variants: 375 observed, 376.15 expected, observed/expected ratio (o/e) 1, 90% interval 0.92 to 1.09. Synonymous variants: 196 observed, 163.09 expected, observed/expected ratio (o/e) 1.2, 90% interval 1.07 to 1.35.
Homologues: Orthologues: chimpanzee MBD3 (100% identical), macaque MBD3 (99% identical), guinea pig MBD3 (96% identical), pig MBD3 (95% identical), rat Mbd3 (95% identical), mouse Mbd3 (94% identical), dog MBD3 (85% identical), tropical clawed frog mbd3 (82% identical), zebrafish mbd3a (76% identical), Drosophila melanogaster MBD-like (36% identical). Paralogues in human: MBD2 (66% identical), MBD1 (31% identical), MBD3L1 (30% identical), MBD3L2 (23% identical), MBD3L5 (23% identical), MBD3L2B (22% identical), MBD3L3 (22% identical), MBD3L4 (22% identical).
Diseases named in the same sentence as MBD3 in open-access papers:
MBD3 is named in the same sentence as 55 diseases in open-access papers, as found by Europe PMC text mining. Sharing a sentence is not in itself a finding about the gene and the disease. The quoted sentences say what the papers report.
breast carcinoma (6 papers, 2013 to 2024). "MBD3/NuRD was reported to regulate epithelial-mesenchymal plasticity and tumor metastasis of breast cancer cells." (PMID 38178023, 2024). "Using the MBD3 subunit as a signal, NuRD was found on CpG-rich promoters, on gene bodies and on enhancers in different breast cancer lines, a distribution that closely resembles the distribution of MLE and Mi-2 overlapping sites." (PMID 25776889, 2015). "Here, we study the localization and function of MBD3, a component of NuRD, in two human breast cancer cell lines using two independent genomic technologies." (PMID 24385926, 2013). "Here, we provide location analysis of endogenous MBD3, a component of NuRD complex, in two human breast cancer cell lines (MCF-7 and MDA-MB-231) using two independent genomic techniques: DNA adenine methyltransferase identification (DamID) and ChIP-seq." (PMID 24385926, 2013). "As was the case with DamID data, genes marked by MBD3 in MCF-7 cells were enriched in transcripts defining the luminal gene expression pattern in breast cancer; genes marked by MBD3 in MDA-231 cells were enriched in transcripts defining the basal transcriptional program." (PMID 24385926, 2013). "MiR-8073 binds to at least five mRNAs (FOXM1, MBD3, CCND1, KLK10, and CASP2) in various cancers such as colon, pancreatic, and breast cancer in vitro and determines the gene and protein expression levels of these five targets." (PMID 35163589, 2022).
colon cancer (5 papers, 2004 to 2023). "To further discuss the clinical significance of MBD3 in colon cancer, we used calibration analysis to predict the association of MBD3 expression with 1, 2, and 3-year prognosis in colon cancer patients." (PMID 37370795, 2023). "The clinical relevance of MBD3 in colon cancer was analyzed by analytical techniques to identify its involvement in colon cancer pathways and EMT." (PMID 37370795, 2023). "The findings suggest that MBD3 plays an important role in multiple aspects of colon cancer, especially the EMT process, which promotes metastases and leads to poor prognoses, and has potential biological value as a novel therapeutic target." (PMID 37370795, 2023). "Our findings demonstrate MBD3 as a potential prognostic marker and therapeutic target for colon cancer." (PMID 37370795, 2023). "Through functional enrichment analysis of co-expressed genes of MBD3 in colon cancer, we identified its involvement in multiple pathways of colon cancer biological processes and its association with EMT." (PMID 37370795, 2023). "Subsequently, the efficiency of knockdown and overexpression of sh-MBD3 and Flag-MBD3 was verified, and the results showed that the relative expression of MBD3 in colon cancer cells transfected with sh-MBD3 was significantly lower than in the control group." (PMID 37370795, 2023). "To further explore the clinical significance of MBD3, we conducted an analysis of its expression differences across various tumors, with particular focus on colon cancer, utilizing a combination of TCGA and GTEx databases." (PMID 37370795, 2023). "Pathological examinations, western blotting, and qRT-PCR in vitro and in vivo validated MBD3’s differential expression in colon cancer." (PMID 37370795, 2023). "In summary, this study has identified the potential role of MBD3 in colon cancer through bioinformatics and has evaluated its significance through a range of analytical techniques." (PMID 37370795, 2023). "Since the transcription factor c-JUN binds to Nanog promoter to express higher level of stem-like genes in human colorectal cancer, and MBD3 can repress c-Jun transcription in colon cancer cells, we analyzed c-JUN expression in iCSCs." (PMID 27894081, 2017). "We subsequently verified the effect of MBD3 on tumor growth in animal models through nude mouse tumorigenesis experiments and further confirmed its impact on colon cancer migration, invasion, and proliferation through transwell and CCK8 experiments in colon cancer cell lines." (PMID 37370795, 2023). "Additionally, pattern animals that meet the necessary conditions will need to be constructed to further elucidate the mechanism of MBD3 in colon cancer." (PMID 37370795, 2023). "MBD3 is expected to be a therapeutic target for colon cancer." (PMID 37370795, 2023). "QRT-PCR and Western-blot showed that MBD3 was differentially expressed in colon cancer cell lines, among which the expression level was the highest in the SW620 cell line, the lowest in the CaCO2 cell line, and the second and third in the HCT116 and SW480 cell lines, respectively." (PMID 37370795, 2023). "However, the expression level of MBD3 in colon cancer cells transfected with Flag-MBD3 plasmid was significantly higher than in the control group." (PMID 37370795, 2023). "Functional enrichment analysis has confirmed the association between MBD3 and EMT in colon cancer." (PMID 37370795, 2023). "Functional enrichment analysis confirmed the association between MBD3 and EMT in colon cancer." (PMID 37370795, 2023). "However, the specific molecular mechanism of MBD3 on colon cancer EMT requires further investigation." (PMID 37370795, 2023). "However, the role of MBD3 in colon cancer remains to be fully elucidated." (PMID 37370795, 2023).
colon cancer (continued). "In addition, Mbd3/NuRD coordinates cytosine methylation by recruiting DNA methyltransferases to the promoters of tumor suppressor genes in colon cancer cell and leukemia cell lines, and depletion of Mbd3 results in reduced DNA methylation levels at some locations in ES cells." (PMID 27849519, 2016). "However, MBD3’s precise role in colon cancer remains unclear and warrants further investigation." (PMID 37370795, 2023). "LKB1/STK11, however, is rarely involved in sporadic colon cancer cases and at most 33% of NSCLC cases, leading us to consider the role of MBD3 as an alternative tumour-suppressor gene on this location." (PMID 15138480, 2004). "While MBD3’s significant role in pancreatic cancer EMT has been established, its precise role in colon cancer remains unclear and requires further investigation." (PMID 37370795, 2023). "However, the role of MBD3 as a key molecule affecting EMT and metastasis in colon cancer has yet to be fully explored." (PMID 37370795, 2023). "The expression of MBD3 in colon cancer samples was significantly higher than in normal colon tissues (p < 0.001)." (PMID 37370795, 2023). "Furthermore, analysis of single-cell sequencing and clinical data for colon cancer has revealed a negative correlation between MBD3 expression and clinical indicators such as survival prognosis." (PMID 37370795, 2023). "Moreover, analysis of single-cell sequencing and clinical data for colon cancer revealed MBD3 expression’s negative correlation with clinical indicators such as survival prognosis." (PMID 37370795, 2023).
liver cancer (4 papers, 2017 to 2023). An epithelial or non-epithelial malignant neoplasm that arises from the liver. "In liver cancer, MBD3 has been shown to promote tumor cell growth, angiogenesis, and metastasis by inhibiting the tumor suppressor tissue factor pathway inhibitor 2 (TFPI2)." (PMID 37370795, 2023). "MBD3 has been demonstrated to promote the metastasis and growth of various digestive tract tumors, and, in liver cancer, it can enhance the growth, angiogenesis, and metastasis of tumor cells by inhibiting the tissue factor pathway inhibitor 2 (TFPI2)." (PMID 37370795, 2023). "Our results suggest that c-JUN activates CSCs-related genes in liver cancer stem cells, but more studies are needed to understand the network of MBD3, c-JUN, EMT and CD44." (PMID 27894081, 2017). "In liver cancer, the MBD3-NuRD complex inhibited the induction of cancer stem cells (CSC) whereas knockdown of MBD3 upregulated the expression of CSC-related genes." (PMID 31245293, 2019). "We showed that suppression of methyl-CpG binding domain protein 3 (MBD3), a core subunit of the NuRD repressor complex, together with OSKM transduction, induces conversion of liver cancer cells into stem-like cells." (PMID 27894081, 2017).
pancreatic cancer (4 papers, 2022 to 2024). "In pancreatic cancer, MBD3 has been shown to inhibit EMT through the TGF-β/Smad signaling pathway and stemness through the Hippo pathway." (PMID 37370795, 2023). "In pancreatic cancer, MBD3 regulates pancreatic cancer stem cell stemness, interacting with YAP, suppressing YAP nuclear translocation and thus suppressing both Hippo signaling and Sox2 expression." (PMID 36833308, 2023). "In pancreatic cancer, MBD3 can inhibit the epithelial–mesenchymal transition (EMT) process through TGF-β/Smad signaling transduction and suppress the stemness of pancreatic cancer cells through the Hippo pathway." (PMID 37370795, 2023). "In pancreatic cancer cells, MBD3 inhibits EMT via TGF-β/Smad signaling." (PMID 38178023, 2024). "Previous research has established MBD3’s significant role in pancreatic cancer EMT." (PMID 37370795, 2023). "In hepatocellular carcinoma, MBD3 promotes metastasis by inhibiting the tumour suppressor tissue factor pathway inhibitor 2, while MBD3 inhibited epithelial-mesenchymal transition (EMT) via TGF-β/Smad signalling in pancreatic cancer cells." (PMID 38178023, 2024). "Previous studies have reported that MBD3 has the highest cancer mutation rate in pancreatic cancer, and some research has shown that MBD3 has an anti-tumour effect in pancreatic cancer; specifically, it can inhibit the EMT of pancreatic cancer cells through TGF-β/smad signaling pathway." (PMID 35501390, 2022).
autism (3 papers, 2013 to 2023). Persistent deficits in social interaction and communication and interaction as well as a markedly restricted repertoire of activity and interest as well as repetitive patterns of behavior. "Among the 29 TFs activated in male PD patients, ADNP, JUN, MBD3, PRDM14, and ESR1 have known associations with neurodegenerative disorders such as Alzheimer's disease, mental retardation, schizophrenia, and autism." (PMID 36414996, 2022). "TRIM27 is a DNA-binding protein associated with the nuclear matrix and interacts with methyl-CpG-binding domain (MBD) proteins, including MBD2, MBD3 and MBD4, and rare autism-specific protein-changing alterations have been observed both in MBD3 and MBD4." (PMID 24047820, 2013). "Interestingly, pathogenic variants of MBD3 have been found in patients with non-verbal autistic disorder." (PMID 37190088, 2023).
colitis (3 papers, 2019 to 2021). Inflammation of the colon. "We observed that adoptive transfer of Mbd3−/− and circKcnt2−/− ILC3s caused more severe innate colitis compared to WT ILC3s." (PMID 32796851, 2020). "Furthermore, Mbd3 deficiency causes severe colitis after DSS treatment." (PMID 32796851, 2020). "To further determine the physiological role of Mbd3 in the modulation of ILC3s and intestinal innate colitis, we generated Mbd3−/−Rag1−/− mice." (PMID 32796851, 2020). "Of note, with anti-IL-17 antibody treatment, adoptive transfer of Mbd3−/− and circKcnt2−/− ILC3s induced attenuated innate colitis, indicating that IL-17 induced by ILC3s plays a critical role in circKcnt2-mediated inflammatory inhibition." (PMID 32796851, 2020). "HA 35 KDa appears to mimic the effects of bulk HM HA, increasing expression of mBD-3, the murine equivalent of hBD-2, and modulates epithelial zonula occludens-1 (ZO-1) expression, preventing bacterial translocation in multiple models of colitis." (PMID 34204790, 2021). "Importantly, with DSS treatment, Mbd3−/−Rag1−/− and circKcnt2−/−Rag1−/− mice display severe innate colitis, whereas Batf deletion promotes colitis resolution." (PMID 32796851, 2020). "Gut-specific conditional deletion of mbd3 mice showed a large increase in proliferating cells in the colon after DSS treatment compared to control animals, markedly increased susceptibility to colitis-induced tumorigenesis via c-Jun-MBD5/NuRD-AP-1 signaling." (PMID 31998373, 2019). "Furthermore, Mbd3−/−Rag1−/− and circKcnt2−/−Rag1−/− mice develop severe innate colitis following dextran sodium sulfate (DSS) treatments, while simultaneous deletion of Batf promotes colitis resolution." (PMID 32796851, 2020).
colorectal cancer (3 papers, 2017 to 2019). A primary or metastatic malignant neoplasm that affects the colon or rectum. "Like Mbd3, other Mbd proteins, especially Mbd2 and Mbd4, are associated with progression of cancer such as colorectal cancer, albeit by different mechanisms." (PMID 28467410, 2017). "Finally, we found that SMARCA5, MBD3, VPS53, EHD4 are estimated to mediate the regulation of miR-4701-3p and miR-4793-3p on colorectal cancer cell apoptosis, which targets ATP-dependent chromatin remodeling pathway and endocytic recycling pathway." (PMID 31998373, 2019).
hepatocellular carcinoma (3 papers, 2022 to 2024). A malignant tumor that arises from hepatocytes. "IHC score staining of the 227 cases showed that the average expression intensity of MBD3 in the adjacent normal liver tissue was 1.655 ± 2.748, while the average in the hepatoma tissues was 5.667 ± 3.504." (PMID 35501390, 2022). "The effects of MBD3 on hepatoma cells growth and metastasis were investigated, and the mechanism was explored." (PMID 35501390, 2022). "Taken together, these clinical data suggest that hepatomas with high-MBD3 expression were more prone to relapse and metastasis." (PMID 35501390, 2022). "The results showed that MBD3 protein was primarily located in the nucleus of hepatoma cells and normal hepatocytes, and its expression levels were significantly upregulated in hepatoma tissues compared with the adjacent normal liver tissues (P < 0.0001)." (PMID 35501390, 2022). "To further evaluate the impact of MBD3 on the growth and metastasis of hepatoma cells in vivo, firstly we carried out subcutaneous tumorigenesis experiments in BALB/c nude mice." (PMID 35501390, 2022). "MBD3-knockdown Huh7 hepatoma cells exhibited suppressed invasive potential and proliferative rate." (PMID 39153052, 2024). "Importantly, we also found the co-localisation of MBD3 with CHD4 and HDAC1 in human hepatocellular carcinoma samples." (PMID 35501390, 2022).
keratitis (3 papers, 2015 to 2025). A corneal disease that is characterized by inflammation of the cornea. "mBD3 was differentially expressed in mice cornea; FHL and zinc-alpha-2 glycoprotein were differentially expressed in the tears of patients with keratitis infected by A. flavus and Fusarium spp." (PMID 40521031, 2025). "Our findings that transcripts for the antimicrobial peptides mBD2, mBD3 and CRAMP were increased in Pglyrp-2-/- may in part explain the observed improvement in bacterial clearance and efficacious resolution of keratitis in these mice." (PMID 26332373, 2015). "Although we did not see elevation of mBD3, nor test mBD1 after GLY treatment, we did observe reduction in IL-10 (mRNA), suggesting that a similar mechanism may be operative in the keratitis model." (PMID 27792814, 2016).
lung carcinoma (3 papers, 2004 to 2025). "MBD3 is a member of the methyl-CpG-binding domain family and is located on chromosome 19p13.3, a region of loss of heterozygosity in colon and lung cancers." (PMID 15138480, 2004). "We therefore performed a mutation screen, expression study and methylation status assay to investigate the possible role of MBD3 in the aetiology of colon and lung cancers." (PMID 15138480, 2004). "Several studies have demonstrated that MBD3 is reduced in gastric, pancreatic, colon and lung cancers, suggesting that its downregulation may contribute to carcinogenesis." (PMID 35501390, 2022). "In summary, we conclude that MBD3 is not a major target of genetic or epigenetic alteration in colon and lung cancer." (PMID 15138480, 2004).
alcohol (2 papers, 2013 to 2023). "MBD3 and DEGs were mainly enriched in: Systemic lupus erythematosus, Alcoholism, Neutrophil extracellular trap formation, Olfactory transduction and Taste transduction, GSEA functional enrichment suggests that they are involved in Transport of Small Molecules and Hemostasis." (PMID 37370795, 2023).